HOTAIR (HOX transcript antisense RNA)
Diseases named in the same sentence as HOTAIR in open-access papers (continued):
Sharing a sentence is not in itself a finding about the gene and the disease.
cancer (continued). "HOTAIR is overexpressed in various cancers, e.g. of the breast, the lung, esophagus, pancreas and the gastrointestinal system and is usually associated with an aggressive phenotype." (PMID 25994132, 2015). "Whereas some well known lncRNAs, such as HOTAIR are known to be deregulated in a wide spectrum of cancers, several lncRNAs have been described to be highly specific for a particular cancer type." (PMID 25954300, 2015). "Since HOTAIR plays important regulatory roles in the malignant tumor progression through regulating cell cycle, apoptosis, invasion and metastasis, a high expression of HOTAIR correlates highly with some epithelial tumor metastasis and invasion." (PMID 25792974, 2015). "As the expression pattern of HOX genes is specific to each tissue it would in fact be remarkable, if HOTAIR overexpression elicited the same response in each cancer type." (PMID 25994132, 2015). "For example, HOTAIR is a well-known lncRNA whose dysregulation correlates with poor prognosis and malignant progression in many forms of cancer." (PMID 26485761, 2015). "Understanding the biological roles of HOTAIR in different types of cancer helps us to determine the efficiency of this lncRNA as a diagnostic or predictive biomarker." (PMID 25859406, 2015). "The lncRNA HOTAIR is reported to be overexpressed in many different cancers and to contribute to an aggressive phenotype." (PMID 25994132, 2015). "Between these groups, Kaplan-Meier-analysis displayed a significant longer cancer-specific survival for patients with low HOTAIR expression (p = 0.009)." (PMID 25994132, 2015). "The best studied of these lncRNAs, HOTAIR, is expressed from the posterior region of the HOXC cluster and is implicated in the regulation of development and in cancer." (PMID 25994132, 2015). "Different studies provide some evidence for the crucial roles of HOTAIR in the initiation and progression of various cancers." (PMID 25859406, 2015). "We selected those genes with functions known to be associated with cancer of which there were 12—SNVs: NOTCH2, PIK3CG, IL2RB, BAI3, FREM2 and RERE; indels: UTRN, CDHR3, NCOA5, CABYR, HOTAIR and FOLH1." (PMID 26017033, 2015). "To date, accumulating evidence indicates that HOTAIR plays a critical role in cancer progression and metastasis." (PMID 26172293, 2015). "In spite of this, HOTAIR has been demonstrated in promoting metastasis in other cancer types via the modulation of epigenome." (PMID 26230711, 2015). "In this review, we describe the molecular function and regulation of HOTAIR and its role in different types of cancers." (PMID 25859406, 2015). "Our findings have therefore enriched the body of literature pertaining to the identification of molecular subtypes within various cancers, further justifying HOTAIR expression deregulation in HPV16 positive CaCx cases as a potential diagnostic marker." (PMID 26152361, 2015). "In HCC, however, to date, only a few studies implicated lncRNAs, such as MALAT1, HOTAIR, HOTTIP/HOXA13, H19, HULC, MEG3, in the cancer pathogenesis." (PMID 25686840, 2015). "HOTAIR promotes cancer progression in various ways, including dependents EZH2 to promote cell cycle progression, regulating PTEN methylation and maintaining the stemness of cancer cells." (PMID 25928008, 2015). "Our findings are consistent with the view that HOTAIR modulates the epigenome at the level of the DNA methylome in both cancer cells and tumour stroma." (PMID 26497652, 2015). "Elevated levels of HOTAIR are predictive of unfavorable prognosis in other cancers (such as colon and liver) pointing to a more general role in oncogenesis." (PMID 25774169, 2015). "In the case of stages, a significant increase (p = 0.006) in HOTAIR expression was found according to cancer progression, finding higher levels when the cancer spreads across muscle layers (T2 stage) to the surrounding organs (T4)." (PMID 26457124, 2015).
cancer (continued). "Further evidence indicates that HOTAIR reprograms the chromatin state to promote cancer metastasis and primary tumor growth in vivo." (PMID 26448942, 2015). "Dysregulation of lncRNA HOTAIR has been considered a primary feature of several human cancers including breast cancer, hepatocellular carcinoma, colorectal cancer, pancreatic carcinomas, gastrointestinal stromal tumors, and human EOC." (PMID 25792974, 2015). "The expression of HOTAIR is regulated by several tumor suppressive miRNAs, such as miR-34a and miR-141 in cancer cells." (PMID 25491133, 2014). "HOTAIR is highly expressed in several cancer types (prostate, breast, colorectal, liver, pancreas, laryngeal cancer) and is associated with poor outcome and metastasis in breast cancer." (PMID 25322458, 2014). "We found that patients with increased HOTAIR expression had a worse survival in all four cancer types studied." (PMID 25275300, 2014). "Analysis of approximately 100 cancer tissues showed that HOTAIR expression was significantly higher in cancer tissues than in normal tissue samples (p = 0.002)." (PMID 25334066, 2014). "In a previous study, the lncRNA HOTAIR was upregulated and promoted cancer metastasis and predicted poor prognosis in ESCC." (PMID 24888564, 2014). "Accumulating evidence indicates that the long non-coding RNA HOTAIR plays a critical role in cancer progression and metastasis." (PMID 24775712, 2014). "Understanding the precise molecular mechanisms by which HOTAIR regulates PRC2 will be a critical first step in exploring this potential new avenue in cancer therapy." (PMID 25334066, 2014). "By combining HRs from Cox multivariate analyses, we found that HOTAIR expression was an independent prognostic factor for cancer patients (pooled HR 2.26, 95% CI: 1.62–3.15)." (PMID 25157956, 2014). "The prevailing mechanism of HOTAIR-mediated regulation of cancer is that elevated expression of HOTAIR shifts PRC2-mediated gene repression from tumorigenic genes to tumor-suppressive genes." (PMID 25491133, 2014). "HOTAIR, a newly discovered long intergenic noncoding RNA (lincRNA), has been reported to be aberrantly expressed in many types of cancers." (PMID 25157956, 2014). "Known lung cancer-associated lncRNAs are few and include HOTAIR, H19, ANRIL, MALAT1 (lung adenocarcinoma associated transcript 1), SCAL1 (smoke and cancer-related long-chain non-coding RNA1), lncRNA AK126698, and lncRNA GAS6-AS1 (GAS6 antisense RNA1)." (PMID 25089627, 2014). "A large number of studies have shown that HOTAIR is up-regulated in various cancers and correlates with carcinogenesis and metastasis, as well as poor prognosis." (PMID 25387074, 2014). "HOTAIR expression is deregulated in a spectrum of cancers and HOTAIR expression correlates with patient survival." (PMID 25275300, 2014). "LncRNAs, e.g., HOTAIR, are deregulated in many cancer types, affect signaling pathways that promote cancer and modulate gene expression." (PMID 25275300, 2014). "In a previous study, the upregulation of the lncRNA, HOTAIR, which was originally discovered in breast cancer tissues, was demonstrated to promote cancer metastasis and predict poor prognosis in ESCC." (PMID 24888564, 2014). "In this meta-analysis, we have examined the prognostic role of HOTAIR in cancer and the relation between HOTAIR and clinicopathological characteristics of cancer." (PMID 25157956, 2014). "Although HOTAIR expression is considered to relating to clinical prognosis of multiple cancers, the impact of HOTAIR on the development of cancer still remains elusive." (PMID 25303230, 2014). "HOTAIR was significantly deregulated in a significant percentage of patients from the different cancer types examined." (PMID 25275300, 2014). "Subgroup analysis showed that HOTAIR abundance was an independent prognostic factor for cancer metastasis (HR 3.90, 95% CI: 2.25–6.74)." (PMID 25157956, 2014).
cancer (continued). "Flow cytometric analysis indicated knockdown of HOTAIR suppressed cancer cells proliferation (S-phase fraction) in vitro while miRNA-130a inhibitor rescued the proliferation." (PMID 24953832, 2014). "It is noteworthy that miR-141 is a member of the miR-200 family, one of the most potent miRNA inhibitors of epithelial-mesenchymal transition (EMT), a pathological process that is promoted by HOTAIR in cancer." (PMID 25491133, 2014). "Over-expression of HOTAIR promotes metastasis of breast, pancreatic, endometrial, colorectal, and other cancers." (PMID 24971229, 2014). "Healthy and cancer tissue was compared to demonstrate that HOTAIR is deregulated in many tumor types." (PMID 25275300, 2014). "miRNA-130a has been found to be downregulated in a variety of carcinomas and exhibits tumor-suppressive activity while HOTAIR was demonstrated be an oncogene and upregulated in carcinomas." (PMID 24953832, 2014). "It is conceivable that Myc mediates activation of the HOTAIR gene by Col-1 because the miR-17-92 cluster, another transcriptional target of Myc in cancer cells, is concurrently up-regulated by Col-1 in rBM 3-D culture in our recent report." (PMID 23668363, 2013). "In this study, we found that high expression levels of HOTAIR, a cancer-related lncRNA, correlated clinically with ESCC progression." (PMID 23717443, 2013). "This discrepancy between the two cancer types suggests the presence of yet unidentified epigenetic mechanisms regulating HOTAIR-mediated transcriptional silencing." (PMID 24013378, 2013). "Overexpression of HOTAIR in epithelial cancer cells leads to altered histone H3 lysine 27 methylation and promotes cancer metastasis." (PMID 24069260, 2013). "Recent studies of the individual functionalities of long non-coding RNAs (lncRNAs) in the development and progression of cancer have suggested that HOTAIR is capable of reprogramming chromatin organization and promoting cancer cell metastasis." (PMID 24155936, 2013). "These in vitro findings suggest that the elevated HOTAIR expression in tumor tissues results from cancer cells’ response to Col-1 that is aberrantly enriched in the tumor microenvironment." (PMID 23668363, 2013). "Based on these findings, it is likely that the link between HOTAIR expression and cell proliferation is dependent on the type of cancer." (PMID 24130837, 2013). "Meanwhile, HOTAIR knockdown can inhibit cell invasion and proliferation, alter cell cycle progression and induce apoptosis, indicating that HOTAIR can play a direct role in the modulation of cancer progression." (PMID 24103700, 2013). "Numerous studies have suggested that high expression levels of HOTAIR in many types of cancer potentially correlate with metastasis and poor prognosis." (PMID 23109937, 2012). "Several lncRNAs (e.g., MALAT1, HOTAIR, and ANRIL) are associated with human diseases, including cancer." (PMID 23109937, 2012). "Although, the precise mechanism of HOTAIR activities remains to be elucidated, it is clear that HOTAIR reprograms chromatin state to promote cancer metastasis." (PMID 21489289, 2011). "High levels of HOTAIR expression were found to be correlated with both metastasis and poor survival rate, linking a ncRNA with cancer invasiveness and patient prognosis." (PMID 21489289, 2011). "It was previously demonstrated that HOTAIR promoted the growth of cancer cells and could serve as a strong prognosticator." (PMID 41459628, 2026). "Notably, HOTAIR, an important lncRNA in breast cancer, participates in the epithelial-mesenchymal transition process and sustains the population of cancer stem cells." (PMID 41013839, 2025). "Finally, emerging studies showed that HOTAIR is an important lncRNA increased in the plasma and tissues of several human cancer patients." (PMID 40282449, 2025). "Our findings demonstrate that HOTAIR plays a fundamental role in the reprogramming of two key metabolic pathways in tumor cells, highlighting its potential as a therapeutic target against cancer." (PMID 40072116, 2025).
cancer (continued). "Two epigenetic protein complexes that encourage cancer metastasis use HOTAIR as a scaffold." (PMID 39912983, 2025). "HOTAIR is an lncRNA involved in several cellular processes, including regulation of gene expression, epigenetic modifications, and cancer progression through mechanisms that alter chromatin remodeling, transcriptional regulation, and post-transcriptional processing." (PMID 40801625, 2025). "Recent studies have shown that HOTAIR facilitates protein-protein interactions influencing various pathways such as epigenetic reorganization, protein stability, and signal transduction in cancer." (PMID 40686703, 2025). "Likewise, in EC also the expression of HOTAIR is higher in comparison to the normal endometrial tissue and the level of expression is correlated with the clinical stage of the cancer." (PMID 39912983, 2025). "Similarly, HPV-related cancers exhibit EV-carried oncogenic lncRNAs (HOTAIR, MALAT1) in cervicovaginal fluid for early malignancy detection, and SARS-CoV-2 utilizes platelet-derived EV counts and lipid profiles (GM3) to gauge disease severity." (PMID 40809518, 2025). "Moreover, the expression of EZH2 and HOTAIR have been found to be regulated by estradiol or environmental endocrine disrupting chemicals in several cancers and in vitro." (PMID 40868070, 2025). "Conversely, reducing HOTAIR expression appears to curtail cancer development and tumor growth." (PMID 38329598, 2024). "MALAT1 and HOTAIR showed significant fluctuation in their expression under various cancer types, influencing inflammation, autophagy, migration, metastasis and therapeutic sensitisation, highlighting their potential for acting as a biomarker and therapeutic candidate." (PMID 40176927, 2024). "Additionally, many lncRNAs such as PCGEM1, CTBP1-AS, PCAL7, HOTAIR, CRPC-Lnc#6, SOCS2-AS1, NXTAR and ARNILA associate with ARs in different cancers and modulate various aspects of tumorigenesis and carcinogenesis via diverse mechanisms." (PMID 39199690, 2024). "Therefore, we need to better understand the role of HOTAIR in pan-cancer and its potential prognostic value, as well as the molecular mechanism of its action." (PMID 38696320, 2024). "Specifically, HOTAIR has been identified as a determinant factor in the response of cancer to therapy; in invasion, migration, and proliferation; and in maintaining stemness features and other functional effects, primarily through interactions with other molecules including microRNAs." (PMID 38275875, 2024). "However, in vivo, we found lncRNA-HOTAIR, which can act precisely on cancer cells using peptide nucleic acids (PNAs) bound to pH-(Low) Insertion Peptides (pHLIP) and inhibited the interaction of HOTAIR with EZH2." (PMID 39655078, 2024). "Our results highlight the essential role of HOTAIR in pan-cancer and uridine bypass, suggesting that the HOTAIR/EZH2/UPP1 axis might be a novel target for overcoming CRC." (PMID 38696320, 2024). "Furthermore, we explored the oncogenic role of HOTAIR through cell experiments and found that it potentiates cancer metastasis and tumor progression by recruiting EZH2." (PMID 38696320, 2024). "This critical regulatory role suggests that HOTAIR could serve as a promising therapeutic target in cancers characterized by PTEN downregulation." (PMID 39273054, 2024). "Our analysis reveals that specific lncRNAs, such as MALAT1, HOTAIR, and PVT1, interact with crucial proteins and pathways that govern mitochondrial function and oxidative stress responses, thereby influencing the susceptibility of cancer cells to cuproptosis." (PMID 39325172, 2024). "Thus, the present data and previous studies support the notion that HOTAIR functions as a tumor-promoting factor to conferring radioresistance in cancer progression." (PMID 39055884, 2024).
cancer (continued). "As MALAT1, HOTAIR, and H19 have proven to have roles in cancer progression by regulating proliferation, apoptosis, cell cycle progression, and ROS levels as the main biological functions, these lncRNAs are considered proper targets in the treatment of various malignancies, including AML." (PMID 38777995, 2024). "lncRNA HOTAIR has been reported to play an oncogenic role in many human cancers." (PMID 38696320, 2024). "This discovery reveals the potential role of HOTAIR in the regulation of autophagy and radiosensitivity, and may provide new ideas for cancer treatment." (PMID 39857631, 2024). "In breast cancer, HOTAIR mediates autophagy progression through interactions matrix metallopeptidases, which are critical for cancer invasion; CTNNB1/β-catenin (catenin beta 1) may play a significant role in this process." (PMID 39684286, 2024). "On the contrary, HOTAIR repression has been shown to attenuate tumourigenesis and cancer progression, indicating that it might serve as a prominent mechanism in cancer pathogenesis (Ref." (PMID 38682637, 2024). "Abnormal expression of HOTAIR in digestive cancers has recently been correlated with histopathological variables such as G status, indicating that HOTAIR may act as a prognostic biomarker to predict survival in various types of cancers such as GC and ESCC." (PMID 38339289, 2024). "Overexpression of HOTAIR generally indicates poor prognosis for cancer patients." (PMID 38696320, 2024). "Due to its multiple functions in cancer initiation and progression, and its ability to influence sensitivity to anticancer drugs, it is suggested the possibility of using HOTAIR not only as a prognostic and predictive biomarker but also as a potential therapeutic target." (PMID 38887279, 2024). "Multiple studies have shown that HOTAIR is overexpressed in a variety of cancers, including PTC." (PMID 38339237, 2024). "This suggests that HOTAIR may impact tumor processing and prognosis through its influence on cancer immunity." (PMID 38696320, 2024). "The lncRNA HOTAIR was found to be significantly overexpressed in HCC, and a potential biomarker for lymph node metastasis in HCC, and later implicated in different cancers." (PMID 39484215, 2024). "High HOTAIR expression is associated with poor survival of PTC patients in clinical samples and TCGA data, indicating the potential oncogenic role of this lncRNA in PTC and an association with cancer progression." (PMID 38339237, 2024). "The deregulation of HOTAIR is strongly related to cancer development and progression." (PMID 38887279, 2024). "Two enhancer regions have been reported to control HOTAIR overexpression in different cancer cells." (PMID 37308974, 2023). "Hence, the properties of HOTAIR have aroused interest of using HOTAIR as a potential therapeutic target or biomarker in cancer biology." (PMID 37880710, 2023). "Thus, considering the key role of HOTAIR in many cancers, it can be a promising target for diagnostics and therapeutics." (PMID 36750826, 2023). "Several SNPs of HOTAIR act as potential cancer susceptibility loci but no studies on the association of SNPs in the Saudi population has been reported." (PMID 36980864, 2023). "Finally, we predicted and summarized the main related molecular mechanism of the function of HOTAIR in cancer biology by bioinformatics analysis and systematic review." (PMID 36924407, 2023). "Many scientists have investigated the relationship between cancer prognosis and HOTAIR expression." (PMID 37776415, 2023). "HOTAIR is known as an oncogenic lncRNA in various type of human cancer." (PMID 37152770, 2023). "Canonicalpathways enriched in the molecular mechanism of cancer (P value 2.15E-09), autophagy (P value 2.95E-08),HOTAIR regulatory pathway (P value 3.00E-07), cellularstress and injury, cell cycle and transcriptional regulation, apoptosis,cytokine signaling, and immune response were determined." (PMID 37581432, 2023).